CD44 (CD44 molecule (IN blood group))
Diseases named in the same sentence as CD44 in open-access papers (continued):
Sharing a sentence is not in itself a finding about the gene and the disease.
tumor (continued). "By contrast, tumors derived from CD44+ expressing PDGCs MU028 and MU039 generated a mixture of tumor cells with discrete cells expressing Olig2+, CD44+ or neither marker." (PMID 28241049, 2017). "In human tumors, not only the expression level of CD44 is increased, for solid tumors, CD44 was also reported to be overexpressed in an activated, high-affinity state in tumor-derived compared to non-tumorigenic cells." (PMID 29062810, 2017). "Our group provided evidence of putative stem-like cells in primary Rb tumor cells using a bi-parameter model by flow cytometry with a phenotype of low CD133, high CD44 expression and small sized cells (FSClo/SSClo/CD133lo/CD44hi) expressing progenitor cell markers (PROX1 and SYX1A)." (PMID 29162051, 2017). "PCSC co-expressing CD44/CD24/ESA showed tumor developing potential 100-fold higher than PC that do not express these molecules." (PMID 27999190, 2017). "CD44+/CD133+ cells demonstrate higher clonogenic capacity than CD133− cells in vitro, while higher CD44 expression is demonstrated in nodal metastases, suggesting a role for CD44 in tumor progression." (PMID 28626726, 2017). "CD44 is expressed in various isoforms whose unique functions and relevance to tumor initiation are not yet fully defined." (PMID 29100356, 2017). "In addition to better understand the relationship between CD44 and CD146, this investigation has the potential to provide mechanistic evidence of the role of CD146 as a tumor suppressor of BC via CD44-HA interactions." (PMID 29121955, 2017). "CSCs are characterized by their tumor forming ability and expression of high levels of ATP-binding cassette drug transporters (ABCG2), cell adhesion molecules (CD44), and anchorage independent cell survival proteins (Cyclin D1), which are collectively responsible for chemo-resistance." (PMID 28536422, 2017). "We found that both high CD44/CD24 ratio and ALDH1+ correlated with tumor malignancy." (PMID 29062075, 2017). "Interestingly, AMHRII expression was more pronounced in the CD44/E-Cadherin positive tumor subset, as observed by multiplexed FC, both in the PDX models and human tumor samples." (PMID 29245952, 2017). "Adhesion of cancer cells to vasculature and enhanced expression of CD44 (CD44s and/or CD44v) by angiogenic factors (e.g., VEGF) produced by tumor cells might lead to facilitated extravasation via angiogenesis." (PMID 28326306, 2017). "CD44-positive leucocytes were also found in the spleen of non-treated control HTM but were not detectable in the tumor or liver of these animals." (PMID 27835865, 2017). "Conversely, pharmacologic targeting of Aurora-A restores chemosensitivity through inhibition of SMAD5 transcriptional activity leading to restoration of a more differentiated luminal CD44-/CD24+/PROCR- phenotype with low ALDH1 activity and impairment of tumor stemness." (PMID 29207686, 2017). "Instead, M-GBM cells express the non-conventional CCL5 receptor, CD44, and use this receptor to maintain tumor cell survival." (PMID 28380429, 2017). "In conclusion, our findings revealed that EMP3 might be a potential target for CD44-high GBMs and highlight the essential functions of EMP3 in TGF-β/Smad2/3 signaling activation and tumor progression." (PMID 27527869, 2017). "As expected, after 18 h of treatments, 5 μM dose of Rimonabant failed to reduce CD133+/CD44+ cells, while 10, 15, and 20 μM doses significantly reduce them, in both differentiated tumor cells and CSCs." (PMID 29354056, 2017). "As the tumor microenvironment can regulate stemness and therapeutic resistance of cancer cells, we determined that cancer cells with Crk-induced EMT did not possess enhanced levels of stem cell markers including Nanog, Sox2, Oct3/4, and CD44." (PMID 27027347, 2016). "However, while assessing the expression of CD133, CD44 and CD24 in primary tumor CRC tissue and in SC derived from patient material, we observed a very heterogeneous expression." (PMID 26745821, 2016).
tumor (continued). "Overall, grifolin may potentially develop as a promising lead compound in the intervention of tumor aggressive progression through targeting the interplay between PGC1α and AP-1/LSF-MMP2/CD44 signaling." (PMID 27626695, 2016). "Previous flow cytometric analyses in the same patient cohort revealed elevated levels of CD44+CD45-EpCAM- cells in the ascites of patients with non-miliary tumor spread." (PMID 27665539, 2016). "Based on the protein expression of CD133 and CD44 in the clinical tumor samples, the patient-derived tumor xenograft models were divided into four groups: high CD133 expression, low CD133 expression, high CD44 expression and low CD44 expression groups." (PMID 27329727, 2016). "CD44 contributes in part as a downstream target of Wnt, a gene involved in the maintenance of the CSC phenotype, and has been shown to be essential for Wnt-induced tumor progression in cancers." (PMID 28000766, 2016). "Intriguingly, CD44 has also been reported to function as a co-receptor for several growth factor receptors, such as EGFR and TGFβ receptor; their coupling is believed to be able to enhance the growth factor-driven tumor proliferation and/or metastasis." (PMID 26849234, 2016). "Interestingly, the two tumor initiating populations (ALDH+ cells and ESA+CD44+CD24− cells) only showed limited overlapping." (PMID 26349457, 2016). "In addition, interaction of HA and CD44 promotes EGFR-mediated pathways, consequently leading to tumor cell growth, tumor cell migration, and chemotherapy resistance in solid cancers." (PMID 27200096, 2016). "Like CD44, CD166 has been shown to participate in tumour invasion." (PMID 27465541, 2016). "Different from CD44, CD24 was predominately expressed in advanced NPC tumors, which implies that CD24 may be involved in advanced tumor progression." (PMID 27521216, 2016). "In tumor regions where pMAPK was highly expressed, CD44 was either absent or expressed at a low level." (PMID 27906173, 2016). "73.8% of patients with CD44-negative tumours survived 5 years compared to only 27.1% of patients with CD44-positive tumours (P < 0.001)." (PMID 26839535, 2016). "A significant difference was found in the expression of epithelial and stromal MMP-14 and CD44 between early-stage and advanced-stage patients, MMP-14 being more often expressed in the tumor epithelium in advanced-stage patients than in early-stage patients and less often in the tumor stroma." (PMID 27590006, 2016). "Expression levels of serum CEA, CD133+CD44+CD54+ cellular subpopulation and extranodal tumor deposits showed predictive value for liver metastasis (P<0.05), and the odds ratios are 3.352 (95%C.I., 1.824–6.839), 2.898 (95%C.I.1.374–6.110), 25.820 (95%C.I.5.155–129.322), respectively." (PMID 27764803, 2016). "By contrast, CD44+ cells were identified in a poorly differentiated component of P28 tumor tissue but not in the other two tumor samples." (PMID 27414409, 2016). "In our study the relative CD44 mRNA expression of patients did not correlate with age, sex, history of smoking, tumor size, clinical and pathological LAP and 5 years survival rate." (PMID 28008391, 2016). "Consistent with SAE2 knockdown, IHC staining of tumours in the shSAE2 group showed reduced level of SAE2, as well as reduced level of the CSC markers ALDH1A1 (an isoform believed to be critical for ALDH activity in CSCs30) and CD44, relative to shCtrl cells." (PMID 27465491, 2016). "However, each tumor had a distinct stromal signature in terms of immune cell infiltrate and expression of CD26 and CD44." (PMID 26771241, 2016). "CD56, CD44, CD11a, CD49e, CD45RO, and CD45RA are adhesion molecules and, in malignancy, may be involved in spread of the tumour, immortalisation of the tumour cells and also expressed on normal plasma cells." (PMID 27775669, 2016). "Both the higher expression of CD44 and CD133 may indicate higher exponential replication, and therefore faster tumor growth." (PMID 26840024, 2016).
tumor (continued). "As few as 200 ESA+CD44+CD24− cells were capable to generate tumor in vivo, whereas a 100-fold more cells without these markers isolated from the same tumors were non-tumorigenic." (PMID 26349457, 2016). "HOTAIR also regulates BCSCs, and microarray analysis reveals HOTAIR overexpression upregualtes the genes related to stemness and EMT, such as CD44, STAT3, ALDH2, ZEB1 and VIM, but the tumor initiating frequency in vivo assay are needed to demonstrate the role of HOTAIR in regulating BCSCs further." (PMID 26349457, 2016). "The expression of CD44 and CD24 are highly positive correlation with tumor stage." (PMID 27521216, 2016). "The mean tumor weight at the end point also showed that the tumors with high expression of CD133 or CD44 grew faster than those with corresponding low expression of CD133 and CD44." (PMID 27329727, 2016). "Due to their sheddase activity cleaving off transmembrane proteins, including EGF-receptor ligands, Fibroblast growth factor receptor, CD44, E-cadherin, N-cadherin, Notch, L1, and TNF-α, they regulate paracrine and autocrine signaling pathways involved in tumor growth and progression." (PMID 27542270, 2016). "Other studies revealed CD44 expression in CSCs, including in ESCC tumor-initiating cells." (PMID 27189061, 2016). "In a study of 5 HNSCC tumors, CD44+ALDH+ cells resulted in tumor formation when injected into immunocompromised mice, while CD44+ALDH− cells failed to form tumors." (PMID 26907349, 2016). "This implies that CD44, CD47 and c-met may have synergistic effects on the development of OCCC and probably are biomarkers of tumor stem cells of OCCC." (PMID 25658794, 2015). "The regulation of CD44 alternative splicing during tumor progression is still not completely unraveled." (PMID 25904917, 2015). "Furthermore, the phenotype CD44+CD24−/lowESA+ and high ALDH activity identify cells with increased tumor initiation capacity." (PMID 26372732, 2015). "CD44-positive population was found to be more efficient at proliferating and forming clones than CD44 negative tumor cells." (PMID 25889325, 2015). "The tumor, but not normal muscle, expressed the metastasis protein osteopontin and a single small form (<75 kD) of CD44 that is likely the not alternatively spliced, standard form." (PMID 25861239, 2015). "Interestingly, we found that rapamycin inhibited mTOR signaling in addition to simultaneously downregulating the expression of CD44, SOX2 and MMP-2 and that it affected cell growth and tumor size and weight both in vitro and in vivo." (PMID 26202311, 2015). "Cell surface marker CD44, and the expression of the enzyme aldehyde dehydrogenase (ALDH), partially overlapping within this subpopulation, were assumed as criteria for CSC-enrichment and stem signatures in human BC, correlating to the tumor-initiating ability." (PMID 25884842, 2015). "While 100 CD44+CD133+ cells were sufficient for tumorigenesis, 104 CD44-CD133- cells were required under the same conditions, suggesting that CD44+CD133+ cells had a significantly stronger ability for tumor initiation and represented a stem-like cell feature." (PMID 26172296, 2015). "In aggregate, the functional connections of Wnt activation with increases in tumor generation, metastasis, self-renewal, standard PCSC markers (CD133, CD44, and ABCG2), and pluripotency genes (OCT4 and NANOG) strongly support an important role of the Wnt/β-catenin signaling in promoting PCSLCs." (PMID 26593949, 2015). "In this study, we showed that miR-494 directly binds to the 3′UTR regions of Bmi1 and ADAM10 in HNC-TICs, thus represses the tumorigenecity and TIC properties such as sphere formation capability, CD44 and ALDH1 expression, clonogenic ability, and in vivo tumor initiation incident." (PMID 26090866, 2015). "The CD44 and CD133 markers were used to identify CSCs in tumor tissues." (PMID 26566931, 2015).
tumor (continued). "Indeed, our group found that CD44+/CD133+ cells isolated from PANC-1 cells were capable of forming tumorspheres in vitro, exhibited tumor-initiating potentials in vivo, and profoundly responded to Wnt pathway activation or inhibition." (PMID 26458814, 2015). "In the end, CD44's expression in HCC is related to a higher frequency of extra hepatic metastasis and shortened survival rate and CD24's overexpression in HCC correlates with a more aggressive tumor behavior and poor clinical outcomes." (PMID 26097877, 2015). "Likewise, L1 is expressed on the edges of invasive colon cancers and its metastases and the same holds true for CD44 and CD133, suggesting that these molecules play a role in tumor invasion and thus disease progression." (PMID 25886184, 2015). "Two days following the final treatment, tumor-draining lymph node (TDLN) cells were examined by flow cytometry for the presence of activated, proliferating CD8+ T cells, which were defined as CD8+ cells that express CD25 and high levels of CD44." (PMID 25384911, 2015). "Identified by the cell surface marker CD44+ and the ability to form non-adherent spherical colonies in serum-free media and tumours when implanted into immunocompromised mice, CD44+ gastric CSCs represent ~0.6%–2.2% of the tumour cell population." (PMID 26270676, 2015). "Overexpression of the CD44 3′UTR in MDA-MB231 cells antagonized the effects of the miRNAs on their specific targets and upregulated collagen and fibronectin expression that in turn enhanced tumor cell migration and metastasis in vivo." (PMID 26029216, 2015). "In support, the LAPC9 model harbors tumorigenic subpopulations that can be prospectively enriched using CD44+ and CD44+α2β1+ profiles as well as the SP and ALDH assays with the CD44+α2β1+ subpopulation being the most tumorigenic (i.e., ∼1 tumor-initiating cell in every 20 cells)." (PMID 26246472, 2015). "The simultaneous presence CD44 and pSTAT3 overexpression was recorded in 42.66% of tumor samples and had an additive negative impact on patient OS." (PMID 28031890, 2015). "These interactions suggest that RHAMM may be necessary for CD44-mediated migration during inflammation, wound healing, tumorigenesis, and regulation of stemness/EMT phenotypes within tumor-initiating populations." (PMID 25999946, 2015). "Taken these observations together, CD44-singaling networks-KLF4-p21-Cyclin D1 could explain, at least in part, the molecular events behind the involvement of CD44 in maintenance of tumor initiating cells." (PMID 25605020, 2015). "In comparison, we also tested the effects of the combination of HA-PEI/HA-PEG/MDR1 siRNA CD44 targeted nanoparticle and paclitaxel on tumor growth in drug sensitive SKOV-3 (not express MDR1 and Pgp) xenograft mice model that did not highly express Pgp." (PMID 25687880, 2015). "In contrast, 5 of the 6 mice injected with the 5 × 104 SKOV3 CD117+CD44+-shHOTAIR developed visible tumors on Day 14, Day 16, Day 18, Day 26, and Day 26, respectively, and the remaining 1 mouse did not develop tumor throughout the 64-day observation period." (PMID 25792974, 2015). "Consequently, the second part of the branching process (related to CD47, CD44 and MET) occurs while tumour cells are still in the mammary duct." (PMID 25978366, 2015). "Overall, studies of KAI1/CD82, CD44, MMP7 and β-catenin in relation to tumor metastasis indicate that these molecules are involved in the process of tumor progression through regulating the intercellular adhesion; However, there are few studies on the interaction between them." (PMID 26408312, 2015). "Unlike CD44 expression in tumor samples, CD44 expression in MB cell lines was restricted to those expressing c-Met." (PMID 25625039, 2015). "In contrast, in tumor samples lacking ER expression or with low ER transcriptional activity (as reflected by low PR expression, PRlow), hypoxia promoted the expansion of CD44+CD24−/low cells." (PMID 26372732, 2015).
tumor (continued). "In a number of human malignancies, subpopulations that possess CSC-like properties have been isolated from fresh tumor tissues and permanent cell lines by cell-sorting using the putative CSC-specific markers currently available for this purpose, e.g., CD34, CD44, CD133, ALDH1, EpCAM, and CD271." (PMID 26483189, 2015). "The CSC population, characterized with the cellular identity CD44+/CD24−/lowLin−ALDH-1+ and the capacity to recapitulate the phenotypic heterogeneity of the primary tumour when injected into secondary NOD/SCID mice, has been demonstrated to display active Hh signaling to maintain stemness potential." (PMID 26270676, 2015). "In addition to laminin-111, tumor cells growing alone secreted laminin-5, perlecan, MMP-7, TIMP-1 and CD44." (PMID 25885552, 2015). "Compared with the mice injected with CD117+CD44+-scramble, no tumor cell metastasis was found in the lung tissues of the nude mice 64 days after they were injected with the CD117+CD44+-shHOTAIR." (PMID 25792974, 2015). "Importantly, we also found decreased CD44 expression, with altered EMT markers for the decreased vimentin and increased E-Cadherin in the tumor with salinomycin treatment compared to those from control group." (PMID 25483103, 2015). "Importantly, number of genes responsible tumor immune responses and desmoplastic reaction; Mst1r, TGFβr1, TGFβr2, VEGFa, CSF-1, SDF-2, CD44, IL-6ra, PD1, CD68, CD163, fibronection and MMPs were significantly reduced." (PMID 26429877, 2015). "Positive paracrine and autocrine feedback loops between tumor and stromal cells can be initiated by inflammatory mediators such as IL-1α and TGFβ that increase HA synthesis and expression of both RHAMM and CD44, which collectively sustain cell migration and invasion within cancerized stroma." (PMID 26106384, 2015). "For example, attempts to isolate bladder CSCs based on the basal cell surface marker CD44 expression showed substantial variation among basal tumor subtypes and have been unsuccessful in non-muscle-invasive tumors." (PMID 26452033, 2015). "Moreover, since CD44 knockdown represses Akt phosphorylation and growth of PC-3 cells, inhibition of CD44 expression by XRN1 is likely critical for XRN1 tumor suppressive function in NEPC cells." (PMID 25797256, 2015). "Interactions of HA with CD44 and HA-mediated motility receptor (RHAMM) contribute to CLL cell localization, and hence CLL pathophysiology, by shaping homing, interstitial migration, and adhesion of the tumor cells." (PMID 25941526, 2015). "Correlation of these subpopulations with the mode of peritoneal tumor spread revealed an over-representation of CD44+/CD45− cells in non-miliary in both, A and S (median 37.5% versus 14.0%, p = 0.033 and 18.5% versus 5.7%, p = 0.056, respectively)." (PMID 25991672, 2015). "CD44 staining intensity did not vary significantly by tumor grade, although it decreased slightly with grade in hysterectomy specimens." (PMID 25129125, 2015). "There was a significant correlation between CD44 expression and cancer subtype (intestinal), tumor size (4-8 cm), depth of invasion, no lymphatic/vascular invasion and moderate differentiation." (PMID 25635255, 2014). "Instead, drug-induction suggested decrease for ITGB1/CD29c and ALDH1B1, while CD24, CD44, CD166, ALDH1A1 and Lgr5 were unchanged as detected by signals from microarrays with pooled tumor RNA from indomethacin-treated patients versus pooled tumor RNA from control patients." (PMID 25340937, 2014). "Flow cytometric analysis revealed heterogeneity in the tumor phenotype with respect to expression of CD4 and CD8 with tumor cells isolated from the thymus, spleen and bone marrow expressing both CD4 and CD8 or only CD4 with decreased levels of expression of CD44 and CD25." (PMID 24586935, 2014).